NGF (nerve growth factor)
Diseases named in the same sentence as NGF in open-access papers (continued):
Sharing a sentence is not in itself a finding about the gene and the disease.
cancer (continued). "In this study, tanezumab met the primary endpoint by demonstrating greater improvement in daily average pain intensity at the index bone metastasis cancer pain site at week 8 compared to the placebo, highlighting the potential of anti-NGF therapies to reduce cancer pain." (PMID 40647466, 2025). "Likewise, pro-NGF/NGF pathway activation leads to proliferation and invasion of cancer cells in several types of solid tumors." (PMID 40427122, 2025). "Elevated NGF levels are associated with increased PNI, a hallmark of aggressive cancer behavior." (PMID 41009819, 2025). "The use of anti-NGF antibodies could therefore represent a valid adjunct in the palliative management of cancer pain." (PMID 41301953, 2025). "NGF and inflammation have many meeting points and often act in a unanimous way to induce cancer." (PMID 38392180, 2024). "However, further research is needed to fully understand the complexities of NGF signaling in different cancer types and to develop effective and safe targeted therapies." (PMID 38392180, 2024). "Aside from nerve cells, NGF affects cancer cells, promoting their growth." (PMID 39429264, 2024). "Therefore, there is significant interest in the antibodies that target TrkA/NGF as a treatment for various cancers." (PMID 38791953, 2024). "Two noteworthy contributors are Hondermarck H and Monje M. Hondermarck H who joined this field of research early and have been working on how the nervous system affects various cancer progressions since 2012, including nerve fibers, nerve growth factor, neurotransmitters, and their receptors." (PMID 39268034, 2024). "This study explores the hypothesis that inflammatory cell type-derived NGF-driven nociceptor sensitisation plays an integral part in the development of delayed pain behavioural phenotype in paediatric cancer survivors." (PMID 39428813, 2024). "Regarding under-expressed miRNAs in CD, target genes were also found to be associated with inflammatory pathways, but among the most significantly altered pathways (top 10) were axon guidance, pathways in cancer, membrane trafficking, and signaling by NGF, among others." (PMID 38398024, 2024). "Within tumors, nerve cells release several neurotrophic factors that can modulate the proliferation and phenotype of cancer cells, including Nerve Growth Factor (NGF), Neurotrophins (NT), Brain-Derived Neurotrophic Factor (BDNF) or Glial Cell Line-Derived Neurotrophic Factor (GDNF)." (PMID 38375479, 2024). "Similarly, under-expressed miRNAs in both CD and UC were associated with analogous pathways, mainly axon guidance, pathways in cancer, membrane trafficking, and signaling by NGF." (PMID 38398024, 2024). "When examining the pathways of target genes regulated by under-expressed miRNAs in UC, we identified that among the top 10 altered pathways were axon guidance, pathways in cancer, membrane trafficking, signaling by NGF, and signaling regulating pluripotency of stem cells." (PMID 38398024, 2024). "NGF released by cancer cells can sensitize sensory nerves which in turn results in severe pain." (PMID 39723256, 2024). "Importantly, not only peripheral tissues but also cancer and neuronal tissues are rich sources of NGF." (PMID 39766161, 2024). "NGF can play a significant part in the defense against cancer." (PMID 39346791, 2024). "Moreover, the sophisticated relationship between NGF and cancer biology has profound implications in pediatric oncology." (PMID 39056738, 2024). "Neutralizing NGF antibodies such as tanezumab and fulranumab have been studied and may have the potential to inhibit cancer cell migration with minimal side effects on neural function." (PMID 37566075, 2023). "In ovarian cancer, NGF activates TrkA in granulosa cells, where it acts as an indirect angiogenic factor by increasing the expression of vascular endothelial growth factor, leading to cancer cell proliferation, migration and angiogenesis." (PMID 38049878, 2023).
cancer (continued). "Many studies have reported the importance of the NGF/TrkA axis in cancers." (PMID 37046604, 2023). "TrkA serves as a high affinity receptor for the nerve growth factor (NGF), and therefore binding of a potential ligand results in downstream activation of Ras/MAP Kinase and PI3 Kinase pathways, which are closely associated with several cancers." (PMID 37569654, 2023). "Additionally, they display strong responsiveness to differentiation stimuli, such as nerve growth factor (NGF) or cancer cell supernatants, making them an ideal tool for studying neuronal plasticity in vitro." (PMID 37046688, 2023). "Several lines of evidence support the hypothesis that cancer cell support neurogenesis by secreting different neurotrophic factors such as nerve growth factor (NGF), brain-derived neurotrophic factor (BDNF), and neurotrophin 3 (NT3)." (PMID 36289793, 2022). "NGF was present in the medium of all five cancer cell lines." (PMID 35109895, 2022). "NGF secreted by cancer cells can promote nerve fiber regeneration and recruit nerves." (PMID 35449152, 2022). "Furthermore, they showed that Akt inhibition with MK2206 blocked NGF-induced cancer cell migration and dispersion, which lends more evidence to the link between NGF and PNI in oral SCC and reveals potential targets for therapeutic intervention." (PMID 34885121, 2021). "During its development, cancer may release pain factors, including vascular endothelial growth factor, nerve growth factor, protease, prostaglandin, endothelin and bradykinin, which may further aggravate cancer pain." (PMID 33907102, 2021). "Nerve growth factor, initially identified as a key factor for neuronal survival and differentiation, turned out to be a multifaceted molecule with pleiotropic effects in quite divergent cell types, including cancer cells." (PMID 34268306, 2021). "In addition, scRNA-seq revealed upregulation of several cancer-associated (Il-4/Il-13, Hsf1/HSP), oncogenic (TGFβ, NGF, FGF, MAPK) and self-renewal (Wnt, Notch) pathways in p63+/−;ErbB2 luminal cells and PIMECs per se." (PMID 34023861, 2021). "NGF-siRNA-loaded gold nanoparticles can markedly suppress cancer growth by causing NGF down-regulation without exhibiting any major side effects." (PMID 34943856, 2021). "The authors also showed that NGF enhanced cancer cell migration and invasion in a transwell assay." (PMID 34885121, 2021). "CREB activation has been reported by NGF stimulation in neurons and cancer cells." (PMID 33081171, 2020). "Moreover, NGF/TRKA signaling pathways are associated with the modulation of micro-RNA (miR) transcription and its abundance in cancer cells." (PMID 33081171, 2020). "Further in vitro and in vivo experiments have identified many of the secreted signaling molecules (e.g., acetylcholine, nerve growth factor) that are passed between neurons and cancer cells, as well as the major signaling pathways (e.g., MAPK/EGFR) involved in these trophic interactions." (PMID 33322770, 2020). "Four growth factors (NGF, BDNF, NT-3, and NT-4/5) and 2 types of receptors (Trk tyrosine kinase receptors and P75NTR) constitute the neurotrophin signaling pathway, which is associated with cancer stem cells." (PMID 33224315, 2020). "NGF was strongly expressed in discrete regions within the cancer stroma." (PMID 32155948, 2020). "We are performing BDNF, NGF, FAK, ADRb2 and NLRP3 assessments by qPCR in extracellular vesicles from plasma and platelets by qPCR in advanced cancer patients and preliminary results show that responders correlate with diminishing levels, mainly, of NGF and BDNF (unpublished data)." (PMID 32516941, 2020). "AKT and ERK signalling pathways activated by NGF/TRKA favour cancer cell growth." (PMID 33081077, 2020). "Nerve growth factor (NGF) is the first growth factor discovered from neurons in cancer biology." (PMID 31839752, 2019). "NGF-inhibitor Tanezumab has also shown some success against cancer-induced bone pain in patients." (PMID 31578352, 2019).
cancer (continued). "Furthermore, NGF released by cancer cells promotes neuritic growth, reduces cancer cells’ apoptosis and increases proliferation leading to enhanced cancer aggressiveness." (PMID 31248001, 2019). "The central role of NGF/Trk is in cancer initiation and progression." (PMID 30741921, 2019). "Our analysis revealed that, aside from well-established cancer-related signaling pathways, several novel pathways, including axon guidance, neurotrophin/nerve growth factor signaling, and endocytosis, were found to be involved in the pathogenesis of gastrointestinal cancers." (PMID 29459716, 2018). "The control and balance of the p75 receptor through NGF expression may be a potential target for reprogramming de-differentiated and aggressive neural crest-derived cancers to a differentiated, stable cell type." (PMID 29175861, 2018). "In HSNCC tissue, ISH evidenced that the cancer cell nests were capable of NGF mRNA synthesis." (PMID 29904026, 2018). "The mechanism may involve miRNAs, since NGF interacts with miRNAs for cell survival, which usually co-occurs with cell proliferation in cancer cells." (PMID 29565967, 2018). "In addition, one of the pan-cancer mutational patterns we identified was enriched for several growth factor pathways, including EGF receptor family genes, and FGFR and nerve growth factor signalling." (PMID 29765148, 2018). "When considering NGF-NGFR as a therapeutic target of human malignant tumors, NGF might confer chemoresistance of cancer cells due to the role of NGF in the resistance to oxidative stress and apoptosis." (PMID 28679437, 2017). "Furthermore, cancer cells respond directly to NGF and proNGF, to exacerbate cancer-related phenotypes." (PMID 28282920, 2017). "Overall, these findings are consistent with other studies showing that systemic NGF administration is associated with an increased biological activity of NGF-target cells and not related with the induction of cancer cell proliferation." (PMID 27439311, 2016). "The presence of NGF protein and the expression of NGF-receptors in cancer cells have produced a number of divergent hypotheses as whether NGF is directly involved in cancer cell proliferation and differentiation." (PMID 27439311, 2016). "By the way, the presence of NGF and NGF-receptors in cancer cells raised the question as whether NGF is involved in promoting cell proliferation and eventually cancer cell survival." (PMID 27439311, 2016). "The possibility that NGF in concert with other pro-cancer biological mediators might play a role in cell survival cannot be excluded, but this effect and the underlined mechanisms need to be identified." (PMID 27439311, 2016). "Consequently, patients experience cancer-related bone pain which can be relieved by the inhibition of nerve growth factor (NGF)." (PMID 26284194, 2015). "NGF facilitates cancer cell proliferation by binding to TrkA receptors in the perineurium." (PMID 26576639, 2015). "Our data also highlighted the importance of cancer cells in driving function-evoked pain and neuronal plasticity (i.e., receptor upregulation and functional modulation) by tumorigenic mediators including NGF." (PMID 24903857, 2014). "Such plasticity is modulated by NGF, another major cancer-released mediator." (PMID 24903857, 2014). "An intriguing question is whether such activity would release NGF from the nerves and thus impact upon the cancer VGSCs." (PMID 24493753, 2014). "In fact, there is growing evidence that NGF is able to exert a wide spectrum of effects on many other cells as well as being involved in a wide variety of functions, such as angiogenesis mediation and cancer development promotion." (PMID 23637956, 2013).
cancer (continued). "In addition to its neurotrophic effect, NGF has been reported to be up-regulated in several malignant tumors." (PMID 24180625, 2013). "Therefore, NGF has been suggested as a potential therapeutic target for the treatment of malignant tumors, especially in BRCA." (PMID 24180625, 2013). "Furthermore, PEMF exposure enhanced the pro-apoptotic effect of Cl-IB-MECA in cancer cells obtaining an increase of 1.97, 2.64 and 3.24 fold respect to basal condition in untreated or NGF-treated PC12 and U87MG cells, respectively." (PMID 22761760, 2012). "A major question is whether this ectopic sprouting of sensory nerve fibers only occurs when cancer cells express high levels of NGF." (PMID 22640953, 2012). "Our knowledge of NGF signaling in various cancers suggest therapeutic opportunities." (PMID 24212627, 2011). "The present data suggest that early/sustained administration of therapies that block the NGF/TrkA axis may be more effective than late administration in reducing the ectopic sprouting as well as cancer pain." (PMID 21138586, 2010). "The Nerve Growth Factor model paved the way for the discovery of a family of neurotrophins, elucidating mechanisms of neural plasticity, regeneration, and brain aging, with profound implications for the understanding of mental illnesses, neurodegenerative diseases, and cancer." (PMID 42185713, 2026). "NGF may also induce the expression of TRPV1 and it is implicated in cancer progression and CIBP." (PMID 39940997, 2025). "Therefore, anti-NGF mAbs should be applied pre-emptively before histological changes in nerves and bones occur, but compensatory administration could also attenuate cancer pain." (PMID 40783715, 2025). "Blocking NGF and its receptors, or the involved pathways, alongside chemotherapy could sensitize cancer cells to chemotherapy, preventing the development of drug resistance and possibly helping overcome or delay the emergence of drug resistance by targeting multiple pathways simultaneously." (PMID 38392180, 2024). "Furthermore, NGF may attach to the membrane receptor sortilin, which has been demonstrated to participate in cancer growth, and also to neuropilin-1 (NRP1), a nociceptor-enriched co-receptor for NGF that is necessary for the TrkA signaling of pain." (PMID 38392180, 2024). "Cancer cells could exhibit a "neural addiction" property and build up local nerve networks to achieve an enhanced neurotransmitter-initiated signaling through nerve growth factor-mediated axonogenesis." (PMID 38453934, 2024). "Also, NGF plays a significant role in cancer stem cell production." (PMID 39099944, 2024). "Indeed, NGF plays a multifaceted role in human health, ranging from its essential functions in the nervous system to its potential implications in promoting cell proliferation and survival in cancer cells." (PMID 38392180, 2024). "Moreover, melanoma-infiltrating TRPV1+ nociceptors overexpressing CALCA and Trka - a high-affinity receptor for NGF - may promote cancer-induced pain hypersensivity." (PMID 39906323, 2024). "Furthermore, these findings demonstrate the clinical relevance of developing an antibody-based novel analgesic to inhibit NGF-mediated nociceptor signalling, to treat the painful symptoms of chemotherapy induced peripheral neuropathy in childhood survivors of cancer." (PMID 39428813, 2024). "Interestingly, we observed how cancer cells in coculture could show even a higher effect in neuronal precursor differentiation compared to the NGF stimulation alone." (PMID 37046688, 2023). "Thus, NGF signaling from nerves to cancer stem cells via NGFR expression may promote cancer stem cell renewal and proliferation." (PMID 37566075, 2023). "Similarly, the production of NGF by cancer cells in the bone (e.g., derived from primary tumours of the breast and prostate) can lead to sensitisation of sensory neurons directly by increasing the expression ion channels linked to pain signal transduction and transmission." (PMID 36688083, 2022).
cancer (continued). "Thus, it may be useful to decipher the exact role of the Ach–NGF axis in PDAC, as NGF signaling is known to increase cancer cell growth, PNI, and nerve density in this malignancy." (PMID 36358664, 2022). "Interestingly, nerve growth factor (NGF) in combination with GRK2 promotes opioid receptors phosphorylation whilst amplifying the pain, and when treated with anti-NGF therapies, there was significant relief in cancer bone pain by mediating the outcome of GRK2 and arrestins." (PMID 33806057, 2021). "Additionally, NGF induces sprouting and hyper-innervation of bones; thus, an-ti-NGF Abs used to treat cancer pain were largely described to be highly effective in decreasing peripheral nerve sprouting, neuroma formation, and behavioral nociceptive and spinal cord signs in mice." (PMID 34638667, 2021). "Overexpression of the NGF gene in this pathway shows the role of pain caused by cancer growth during inflammation by stimulating TrkA which is a proto-oncogene that is also involved in PI3K activation related to proliferation and differentiation of cancer cells." (PMID 32986378, 2020). "The interactions between NGF and semaphorin 3A could induce cancer cell apoptosis." (PMID 31839752, 2019). "In contrast, binding of NGF or precursor of NGF (proNGF) to p75NTR could induce cell survival or could be pro-apoptotic; therefore, as a consequence, there are conflicting reports for the role of NGF-related signaling in human malignant tumors." (PMID 28679437, 2017). "Therefore, the hypothesis that NGF administration can promote uncontrolled cell proliferation (leading to cancer development) seems to have weak experimental evidence." (PMID 27439311, 2016). "Since the great heterogeneity of cancer cells (stage of differentiation, malignancy and production/release of different ligands) may represent a signal for promoting cell neoplasy, the identification of NGF – cancer cell interaction might clearly establish whether this factor acts as a first signal." (PMID 27439311, 2016). "In addition, a separate subtype of neurons (i.e. IB4(-)/NGF-responsive neurons) could contribute to the residual mechanical allodynia observed in our IB4-SAP treated cancer mice." (PMID 24524628, 2014). "Furthermore, the cancer microenvironment contains many other mediators such as NGF, that could affect P2X2 and P2X3 expression, pharmacology and electrophysiological response in sensory neurons." (PMID 24903857, 2014). "NGF’s impact on the TME extends to pain modulation, particularly in cancers like pancreatic and prostate cancer, where it is highly expressed." (PMID 41009819, 2025). "Coculturing prostate cancer cells with CAFs enhances the expression of critical component of the Hippo signaling pathway, Yes-associated protein 1, which in turn elevates the secretion of NGF and promote the occurrence of PNI in cancer cells." (PMID 40421086, 2025). "The expression levels of BDNF and NGF genes were elevated in the cancer group receiving chemotherapy combined with supplements and chemotherapy combined with aerobic exercise, with BDNF and NGF genes exhibiting a significant increase relative to other groups." (PMID 40989799, 2025). "Conversely, neural structures release factors such as NGF, GDNF, ARTN, and CXCL12 (SDF-1), which act as chemoattractants for cancer cells expressing corresponding receptors." (PMID 40909268, 2025). "NGF activates key signaling pathways, including MAPK and PI3K/AKT, which promote cancer cell proliferation, survival, and migration." (PMID 41009819, 2025). "Although small, these differences affected important signaling pathways (NGF-stimulated transcription, IL-10 signaling, PERK activity) and cancer genes (CBFA2T3, ETV4, FGFR1, GLI1, SGK1, and STAT3)." (PMID 38968069, 2024). "Overexpression of Nodal in pancreatic cells upregulates the expression of NGF, BDNF and GDNF, enhancing the migratory and invasive abilities of cancer cells." (PMID 39119085, 2024).